FTO (FTO alpha-ketoglutarate dependent dioxygenase)
Diseases named in the same sentence as FTO in open-access papers (continued):
Sharing a sentence is not in itself a finding about the gene and the disease.
Obesity (continued). "The FTO protein functions as an N6-methyladenosine demethylase, accelerating RNA changes required for preadipocyte development and hence increasing obesity, a significant CVD risk factor." (PMID 36551003, 2022). "FTO knockout or loss-of-function mutations lead to reduced body weight, and its overexpression contributes to obesity." (PMID 35769384, 2022). "Of several variants in LEP, LEPR, and FTO genes identified and tested for obesity association, only a few have been successfully replicated in different world populations." (PMID 36126070, 2022). "We show a significant modulating interaction between physical activity and FTO rs9939609 on obesity risk." (PMID 36235854, 2022). "To date, publications regarding FTO rs9939609 obesity risk-allele carriers’ interaction with physical activity show inconsistency in different populations, stressing the importance of studying this interaction in different populations." (PMID 36235854, 2022). "Based on a meta-analysis that included 12 eligible studies with 5000 cases and 9853 controls, the FTO rs9939609 polymorphism was significantly associated with an increased risk of obesity." (PMID 36499740, 2022). "The fat mass and obesity-associated (FTO) gene encodes a 2-oxoglutarate-dependent nucleic acid demethylase which is the first well-established obesity-susceptibility gene." (PMID 36213660, 2022). "The fat mass and obesity-associated (FTO) gene is located on chromosome 16, and common polymorphisms in the first intron are strongly associated with obesity." (PMID 35268025, 2022). "The polymorphisms rs9939609 (T/A) and rs17817449 (T/G) in FTO are associated with body weight, BMI, and extreme obesity in the Brazilian population." (PMID 35268025, 2022). "Inactive FTO rs9939609 risk-allele homozygotes had 3.77 times higher obesity risk compared to active homozygotes." (PMID 36235854, 2022). "The strongest shared locus between type 2 diabetes and sleep traits was FTO (lead SNP rs8047587), a well-known gene associated with body mass index, obesity risk, and type 2 diabetes." (PMID 35203577, 2022). "Our findings showing a BMI lowering, protective effect of SNP rs9941349 of FTO gene are contrasting with previous studies conducted on African derived population which showed correlation of polymorphism with extreme obesity." (PMID 36126070, 2022). "Further to its association with obesity, epidemiological studies link FTO SNPs with higher risks of endometrial cancer, breast cancer, pancreatic cancer and melanoma; with some variations among different races." (PMID 35409166, 2022). "A meta-analysis collected and analyzed all these studies suggesting that the rs9939609 has to be considered as the major FTO gene variant associated with overweight/obesity across multiple pediatric populations." (PMID 36452324, 2022). "FTO is the first obesity susceptibility gene confirmed by whole genome scanning and is localized to human chromosome 16q 12.2, is approximately 430 kb, and contains nine exons and eight introns." (PMID 35087575, 2021). "The aim of this study was to determine the role of the m6A demethylase fat mass and obesity (FTO)- associated protein in SA." (PMID 34350169, 2021). "The largest cluster of highly significant genetic variants is located in the FTO (fat mass and obesity associated) gene region on chromosome 16." (PMID 33828129, 2021). "It has been recently demonstrated that, in HEK293T cells, TRMT10A indirectly regulates m6A mRNA methylation by interacting with Fat Mass and obesity-associated protein (FTO)." (PMID 33419045, 2021). "The FTO gene which plays an important role in controlling energy balance has been closely linked to obesity." (PMID 34258276, 2021). "The fat mass and obesity-associated (FTO) gene is a common m6A demethylase that has been proven to have cancer-promoting activity in gastric cancer, breast cancer, bladder cancer and cervical squamous cell carcinoma." (PMID 34725345, 2021).
Obesity (continued). "FTO mutation rs9939609 is associated with not only obesity, but also macronutrient intake, that includes: carbohydrates, protein, polyunsaturated fatty acid (PUFA), and saturated fatty acid (SAFA)." (PMID 34743743, 2021). "The exciting role of IRX3 with obesity came into light with the genome-wide association studies, which identified the direct interaction of IRX3 gene promoter with obesity-associated FTO (fat mass and obesity-associated) gene regions." (PMID 34968255, 2021). "Despite the large number of genetic variants related to obesity, the rs9939609 polymorphism of the FTO gene has been more studied due to its effect on increasing BMI." (PMID 34208143, 2021). "Our observations are consistent with the current state of knowledge, based on the associations of FTO SNPs and markers of obesity." (PMID 34829664, 2021). "Psoriasis and obesity are connected through the human leukocyte antigen-class I allele (HLA-Cw6) locus and alpha-ketoglutarate-dependent dioxygenase (FTO) gene rs9939609." (PMID 34207504, 2021). "FTO rs9939609’s association with obesity and central obesity appeared to be more pronounced with a long-time LTSB (OR = 1.63, 95%CI:1.09–2.45; OR = 1.49, 95%CI:1.09–2.02)." (PMID 33668547, 2021). "Our results indicated that FTO rs8050136 increased the risk of obesity by 77% (OR = 1.77, 95%CI 1.20–2.62) among the participants with a high dietary energy intake." (PMID 33668547, 2021). "The FTO gene was the first reported obesity-associated gene in a genome-wide association study (GWAS) conducted in a Caucasian population." (PMID 34345232, 2021). "Recently, it has been reported that rhein is capable of binding to a AlkB protein, fat mass and obesity-associated (FTO) protein gene, and inhibiting its enzymatic activity." (PMID 34790688, 2021). "Obese adults have a higher prevalence of carrying the specific single nucleotide polymorphisms in the fat mass and obesity‐associated gene (FTO)." (PMID 33190355, 2021). "FTO (fat mass and obesity-associated protein) removes the methylation trace by oxidizing m6A to N6-hydroxymethyladosine or N6-formyladenosine, which are chemically unstable and can hydrolyze to the final adenine product." (PMID 34200507, 2021). "The FTO locus is linked to multiple obesity-related phenotypes through common variant association studies including BMI, fat mass–related traits, and basal metabolic rate, and is considered the strongest genetic risk locus for obesity in humans." (PMID 34290091, 2021). "Whereas the FTO protein has been linked to obesity, the ALKBH5 protein is essential to spermatogenesis." (PMID 34200507, 2021). "According to GWAS, melanocortin 4 receptor (MC4R) gene was reported to the second strongest gene in the causes of obesity next to FTO gene." (PMID 34414818, 2021). "A genome-wide association analysis published in 2007 found that FTO is linked to body mass index (BMI) and obesity." (PMID 34563259, 2021). "Among genetic variations in the human genome, single-nucleotide polymorphisms (SNPs) in the first intron of the Fat mass and obesity-associated gene (FTO) were identified to be most highly associated with obesity risk." (PMID 34795556, 2021). "In previous studies, genetic variants in the FTO (fat mass and obesity-associated) and PPARγ (peroxisome proliferator-activated receptor-gamma) genes have been associated with metabolic disease, body mass index, and obesity among other outcomes." (PMID 33729310, 2021). "The FTO gene has a strong linkage disequilibrium block, within which polymorphisms have been identified that is involved in the development of obesity." (PMID 34837923, 2021). "Several studies have reported a strong association of the FTO polymorphisms with the risk of developing obesity." (PMID 34650918, 2021). "As a result, common variants in the melanocortin 4 receptor (MC4R) gene or fat mass- and obesity-associated (FTO) genes have been listed as obesity-associated SNPs in the GWAS catalog." (PMID 34162918, 2021).
Obesity (continued). "The FTO gene was one of the first genetic loci identified as being associated with bodyweight and strongly linked with the development of obesity." (PMID 34095191, 2021). "FTO is located on chromosome 16, and SNPs in this locus have been linked to changes in fat mass and obesity, which are closely associated with type 2 diabetes." (PMID 34258276, 2021). "There are two known m6A-specific erasers, AlkB homolog 5 (ALKBH5) and fat mass- and obesity-associated protein (FTO)." (PMID 34218271, 2021). "Variants in FTO have been associated with increased obesity and T2D risk suggesting that dysregulated FTO action or expression negatively affects glucose homeostasis in humans." (PMID 33419045, 2021). "A significant association between FTO gene polymorphism and the risk of obesity was elucidated in various populations, suggesting the SNPs of the first intron of the FTO gene are related with adiposity." (PMID 34399781, 2021). "FTO gene SNPs have been intensively reported to contribute to the risk of multiple human malignancies, including obesity and cancer." (PMID 33790968, 2021). "A typical example is that of the fat and obesity-associated (FTO) polymorphisms in the FTO gene (that signifies polygenic obesity)." (PMID 35185512, 2021). "The SNPs of the FTO gene are likely associated with food intake and obesity through modifying the expression of other genes." (PMID 35372458, 2021). "Although the mechanisms by which FTO variants influence obesity are unclear, FTO associations with several eating disorders, including BED, are apparent." (PMID 33807560, 2021). "A strong association between Single Nucleotide Polymorphisms (SNPs) in the first intron of the human FTO (FaT mass and Obesity-associated) gene and an increased body mass index (BMI) was reported in 2007." (PMID 33925955, 2021). "A systematic review and meta-analysis on the effect of the fat mass and obesity-associated (FTO) gene on weight loss demonstrated that the response to weight loss intervention was not significantly different between FTO genotypes." (PMID 33801339, 2021). "Further, m6A is dynamically removed by specific demethylases or “erasers” including fat mass and obesity associated (FTO) and AlkB homologue 5 (ALKBH5)." (PMID 34950106, 2021). "At present, the correlation between the methylation profiles of fat mass and obesity-associated (FTO) gene on the maternal and foetal sides of the placenta and GDM remains unexplored." (PMID 33743080, 2021). "Further, after controlling for the interaction effect, only MC4R rs17782313 was seen to confer risk for obesity in terms of high WHtR among Liangmai whereas FTO rs9939609 was seen to pose significantly reduced risk for WHtR." (PMID 34414818, 2021). "Owing to its role in obesity-predisposing genetic variants, FTO has been shown to have nominally significant associations with cardiovascular disease and is referred to as a cardiovascular biomarker." (PMID 34150765, 2021). "The FTO SNPs, rs1588413, rs9939609 and rs8050136, have been shown to increase obesity risk by 1.27, 1.15 and 2.06 times among Indians, respectively." (PMID 34578944, 2021). "Fat mass and obesity-associated protein (FTO), the first identified N6-methyladenosine (m6A) mRNA demethylase, has been well known for its association with an increased risk of obesity." (PMID 34076564, 2021). "Demethylase FTO is the first gene strongly associated with adipose mass and obesity in β-cells, positively correlated with serum glucose, and closely associated with metabolic alterations, cardiovascular diseases, and T2DM." (PMID 34084770, 2021). "The strongest association observed, and the only loci that reached GWAS significance, was between the rs11642841 within the fat mass and obesity associated (FTO) gene and total sugar intake (p = 3.8 × 10−8)." (PMID 34836209, 2021). "FTO was previously recognized to be associated with the occurrence and development of childhood and adult obesity and type 2 diabetes (T2D)." (PMID 34638947, 2021).
Obesity (continued). "The objective of the study was to assess associations of the rs9939609 FTO allele to glucose tolerance, hepatic and total insulin sensitivity (IS) in individuals with obesity." (PMID 33684170, 2021). "The fat mass and obesity-associated (FTO) gene has been reported as the gene with the strongest significant correlation with obesity." (PMID 34829664, 2021). "Recent studies further demonstrated that two homeobox genes, IRX3 and IRX5, in the vicinity of FTO directly mediate the effects of obesity-risk variants of FTO on body mass and composition regulation." (PMID 34795556, 2021). "The FTO gene is strongly associated with body mass index, obesity risk, the regulation of fat mass, body size, body fat accumulation and body weight." (PMID 34684585, 2021). "Recently, studies have confirmed that the FTO polymorphisms are highly significantly related to obesity-related traits such as body mass index (BMI), hip circumference, total body weight, body fat percentage, and cardiometabolic traits." (PMID 34064570, 2021). "Genetic variants in the FTO gene have been associated with many traits and diseases, such as obesity, lipid metabolism, type 2 diabetes, and MetS." (PMID 34868209, 2021). "One possible mechanisms of the association between FTO with CRC is the role of obesity as a chronic inflammatory stimulus in carcinogenesis." (PMID 34650918, 2021). "FTO, a fat mass and obesity-associated protein, was the first discovered m6A demethylase that, besides, indicated the reversibility of RNA modifications." (PMID 33807762, 2021). "Despite the clear associations and expression dynamics of FTO in obesity, to date, little is known about the contributions and interplay between FTO’s two target modifications—m6A, and m6Am in affecting metabolism." (PMID 34893620, 2021). "Since diabetes is often associated with obesity, the genes related to obesity, such as FTO and MC4R, are often connected with diabetes." (PMID 34943006, 2021). "In fact, in a recent publication, a different expression level of the FTO gene, extensively described as linked to obesity, has been related to the concentration of hormones produced by the adipose tissue, being positively correlated with leptin." (PMID 35071145, 2021). "Another m6A demethylase, FTO, previously linked with obesity and type II diabetes, was gradually discovered to be involved in diverse cancers." (PMID 34239358, 2021). "Whole genome association studies have shown that the FTO gene is closely related to diabetes and obesity." (PMID 34350169, 2021). "Recent studies showed that genetic polymorphisms in the fat mass and obesity-associated gene (FTO) were associated with obesity and dietary intake." (PMID 34743743, 2021). "Fat-mass- and obesity-associated (FTO) gene codes a polypeptide with 505 amino acids and is a common genetic determinant for obesity and cancer." (PMID 34650918, 2021). "In our previous study, we observed an interplay between FTO genetic variants and daily macronutrient intake (carbohydrates, proteins, and fat) with impact on obesity and its metabolic consequences." (PMID 34829664, 2021). "FTO is associated with diabetes and obesity in humans, and recently it has been reported to be also associated with cellular processes, such as adipogenesis, regulation of dopaminergic signaling, and mRNA splicing." (PMID 34199279, 2021). "The fat mass and obesity associated (FTO) gene contains 9 exons and 8 introns, expresses a 410.50 kbp full-length construct, and is located on human chromosome 16." (PMID 34258276, 2021). "The genomic locus of FTO gene, also known as alpha-ketoglutarate dependent dioxygenase, has been strongly associated with BMI and obesity." (PMID 33805312, 2021). "For example, G × E studies observed unclear evidence of physical activity modulating the effects of FTO gene variants on obesity in humans until a study with large sample size (~ 218,000 individuals) confirmed this interaction." (PMID 34172761, 2021).